CLDN4 (claudin 4)
Diseases named in the same sentence as CLDN4 in open-access papers (continued):
Sharing a sentence is not in itself a finding about the gene and the disease.
gastric cancer (continued). "In this regard, PTEN activity has recently been shown to induce an intestinal differentiation of gastric carcinomas by increasing CDX2, claudin-3 and claudin-4 expression, hence supporting this hypothesis." (PMID 21203412, 2010). "In addition, the overexpression of Cldn4 in gastric carcinoma was correlated with improved patient prognosis and overexpression inhibited gastric carcinoma cell migration and invasion, although it did not affect cell growth." (PMID 35006480, 2021). "In contrast, CLDN4 proteins which do not form tight junctions, act as ligand for integrin signaling and promote survival signals and stemness as found in undifferentiated gastric cancer cells." (PMID 32064037, 2020). "Levels of non-tight junction CLDN4 might be affect malignant potential of differentiated type gastric cancer." (PMID 31040910, 2019). "Moreover, CLDN4 may inhibit the proliferation, migration, invasion, and tumogenesis of gastric cancer cells by inactivating the PI3K/Akt signaling pathway, and enhancing the sensitivity of gastric cancer cells to chemotherapy." (PMID 34887379, 2021). "In poorly differentiated gastric cancer, TJ formation is reduced, but EMT is mediated by non-TJ CLDN4." (PMID 36982569, 2023).
pancreatic cancer (39 papers, 2005 to 2025). "By targeting exposed CLDN4, and thus strongly accumulating in pancreatic cancer tissue, D@C-LPs suppressed orthotopic pancreatic cancer growth as well as xenograft pancreatic cancer while causing minimal toxicity to off-target normal tissues." (PMID 37237291, 2023). "Overexpression of tight-junction protein claudin-4 has been detected in primary and metastatic pancreatic cancer tissue and is associated with better prognosis in patients." (PMID 32414951, 2020). "In pancreatic cancer, expression of claudin-4 was associated with significant reduction of in-vitro invasive potential, inhibition of colony formation, as well as reduction of in-vivo metastases." (PMID 25170871, 2014). "On the contrary, in pancreatic carcinoma, overexpression of claudin-4 has been associated with significantly reduced invasiveness both in vitro and in vivo." (PMID 23822740, 2013). "However claudins have also been shown to reduce invasion as claudin-4 expression was associated with a reduction in invasiveness in pancreatic cancer cells." (PMID 21789222, 2011). "Claudin-4 has also been recently considered a potential marker for targeted therapy and chemotherapy in ovarian and pancreatic cancers." (PMID 39458944, 2024). "CLDNs 1, 3, and 7 and are highly expressed in colorectal adenocarcinoma, and CLDN4 staining results were strong in colorectal and pancreatic cancer tissue samples." (PMID 38731853, 2024). "The investigators concluded that 125I-labeled anti-CLDN4 antibody can be used for SPECT-CT to detect pancreatic cancer; however, due to the low-energy gamma photon emission, it can only be used for imaging of small animals, with a sensitive gamma camera." (PMID 38731853, 2024). "In this study, we developed CLDN4-targeting C. perfringens enterotoxin (CPE)-conjugated liposomes (C-LPs) for pancreatic cancer-targeted therapy." (PMID 37237291, 2023). "The high expression of claudin-4 in pancreatic cancer needs to be further investigated and validated." (PMID 36959784, 2023). "Among CLDNs, CLDN4 in particular has been suggested for ligand-receptor binding strategies for improving the efficacy of targeted chemotherapy for pancreatic cancer." (PMID 37237291, 2023). "In this study, we demonstrated rationally designed, CLDN4-targeting liposomes that are highly specific to CLDN4 in vitro and in vivo and efficiently deliver Dox by targeting exposed CLDN4 in pancreatic cancer." (PMID 37237291, 2023). "Before accepting the apparent efficacy of D@C-LP chemotherapy, it is necessary to confirm the rationale of exposed CLDN4 as a therapeutic target in an orthotopic pancreatic tumor model." (PMID 37237291, 2023). "In contrast, immunohistochemical analyses showed significantly elevated CLDN4 exposure on the surface of cells in pancreatic cancer tissues compared with normal pancreatic tissues." (PMID 37237291, 2023). "Here, we sought to develop a CPE17-containing liposome that targets pancreatic cancers through binding to exposed CLDN4." (PMID 37237291, 2023). "Ten days after orthotopic implantation of tumor cells in the pancreas, CLDN4 expression in pancreatic tumor tissues was evaluated by Western blot analysis and immunohistochemical staining." (PMID 37237291, 2023). "C-SNPs with loadings of doxorubicin (DOX-C-SNPs) collocate and target Claudin-4 in pancreatic cancer cells, disrupting TJs while being significantly reduced in normal pancreatic cells." (PMID 36077843, 2022). "Based on the previous studies, CLDN4 showed high expression in many epithelial malignant tumors, such as ovarian and pancreatic cancer." (PMID 33742531, 2021). "[111In]In-cCPE mutants are a useful tool for noninvasive imaging of claudin-4, which is a widely dysregulated and highly prognostic biomarker in pancreatic cancer." (PMID 32414951, 2020).
pancreatic cancer (continued). "In particular, claudin-4 has been shown to be overexpressed in primary and metastatic pancreatic cancer tissue, including pancreatic intraepithelial neoplasia (PanIN), the most common precursor lesion to PDAC." (PMID 32414951, 2020). "[111In]anti-claudin-4 mAb revealed a promising ability to bind to its target antigen in human xenograft models of pancreatic cancer." (PMID 28842811, 2018). "On the other hand, high expression of claudin-4 suppresses invasion and metastasis in pancreatic cancer while in gastric cancer cells similar inhibition is seen without affecting the cell growth." (PMID 30728783, 2018). "[111In]anti-Claudin-4 mAb is a useful tool for the non-invasive SPECT imaging of claudin-4 which is a widely dysregulated and highly prognostic biomarker in pancreatic cancer." (PMID 28842811, 2018). "In human pancreatic cancer cells, phosphorylated claudin-4 by PKC not only increase its mislocalization but also compromised the TJ barrier integrity." (PMID 30728783, 2018). "Gene expression analyses have revealed that claudin-4 is increasingly expressed in pancreatic cancer as it progresses into more advanced stages." (PMID 28842811, 2018). "Antibodies, such as anti-claudin 4 and anti-prostate stem cell antigen, whose receptors are known to be upregulated in both primary and metastatic pancreatic cancers, were used as targeting agents." (PMID 25988156, 2014). "A German group reported that the ectopic expression of claudin-4 in pancreatic cancer cells reduced their invasive potential both in vitro and in vivo." (PMID 24204396, 2013). "Further bioconjugation with pancreatic cancer-specific monoclonal antibodies, such as anti claudin-4, to the functionalized InP/ZnS QDs, allowed specific in vitro targeting of pancreatic cancer cell lines." (PMID 23691472, 2012). "CdSe/CdS/ZnS QDs with improved photoluminescence efficiency and stability as optical agents have been used for the imaging of pancreatic cancer cells using transferring and anti-Claudin-4." (PMID 23691472, 2012). "Some examples include increased expression of CLDN3 and CLDN4 in prostate and uterine cancers, and high CLDN4 expression in pancreatic cancer." (PMID 21303546, 2011). "Mouse Cldn4 is downregulated in EMT in response to SNAI1 and expression of CLDN4 decreases the potential of pancreatic cancer cells to metastasize downstream of both MEK and PI3K." (PMID 20844758, 2010). "For example, iodine-125 radiolabeled anti-claudin-4 antibody has been employed for imaging pancreatic cancer using gamma scintigraphy and single-photon emission computed tomography/computed tomography." (PMID 19360088, 2009). "For example, CLDN3, and CLDN4 have been found frequently up-regulated in ovarian, breast, prostate and pancreatic tumors." (PMID 16836752, 2006). "A recent study identified CLDN4 as a potent inhibitor of the invasiveness and metastatic phenotype of pancreatic carcinoma cells by playing role in the transforming growth factor-β and Ras/Raf signal regulated kinase pathway." (PMID 15743508, 2005). "In vitro and in vivo studies of pancreatic cancer showed that overexpression of CLDN4 enhanced cell-to-cell adhesion and prevented cancer cells from engaging in invasion and distant metastasis via the transforming growth factor beta (TGF-β) and Ras/Raf/extracellular-signal-regulated kinase pathways." (PMID 38731853, 2024). "Furthermore, Michl's team revealed claudin-4 overexpression in pancreatic cancer and illustrated that targeting claudin-4-expressing tumors with CPE resulted in extensive tumor cell necrosis and a substantial decrease in tumor growth." (PMID 37186068, 2023). "Collectively, our findings suggest the possibility that our CLDN4-targeting D@C-LPs could be promising agents for effective pancreatic cancer therapy." (PMID 37237291, 2023). "Thus far, many of the 27 members of the claudin family, including claudin-18.2 and claudin-4, have significantly aberrantly expression in pancreatic tumors." (PMID 36959784, 2023).
pancreatic cancer (continued). "We previously reported that CLDN4-targeting polysialic acid-based nanoparticles could be promising agents for effective pancreatic cancer therapy." (PMID 37237291, 2023). "In another study, Patrick Michl and his team demonstrated that claudin-4 could suppress invasiveness and the metastatic phenotype of pancreatic cancer cells through the TGF-β and Ras signaling pathways." (PMID 37186068, 2023). "Other uses include non-invasive imaging of claudin-4-overexpressing pancreatic cancers using radiolabeled or fluorescently labeled cCpE in conjunction with single-photon emission computerized tomography scanning or fluorescence reflectance imaging and fluorescence-mediated tomography." (PMID 35269525, 2022). "Furthermore, claudin-4 overexpression has been identified as a potent inhibitor of the invasive and metastatic phenotypes of pancreatic cancer cells and correlates with better outcome in PDAC patients." (PMID 32414951, 2020). "Similarly, overexpression of claudin-6, -7, or -9 enhanced invasiveness and proliferation of an adenocarcinoma cell line, and CLDN4 and 18 were upregulated in pancreatic cancer tissues." (PMID 31783547, 2019). "Specific examples include increased expression of claudin-3 and -4 in types of prostate and uterine cancer, high claudin-4 expression in pancreatic cancer, downregulation of claudin-7 in head and neck and metastatic breast cancer, and an increase in claudin-3 and -4 in breast cancer." (PMID 25120725, 2014). "Claudin-4 expression suppresses cell invasion and metastasis in pancreatic cancer." (PMID 24009024, 2013). "A study into the regulation of claudin-4 by TGF-β revealed that this cytokine downregulated claudin-4 expression within pancreatic cancer, which may be the mechanism by which TGF-β promotes tumour invasion." (PMID 18648369, 2008). "It is not known what regulates claudin-4 expression; however, studies in pancreatic cancer have implicated the TGF-β pathway." (PMID 18648369, 2008). "In addition, our data showing overexpression of CLDN4 in pancreatic cancer is also in agreement with previous reports." (PMID 16836752, 2006). "Interestingly, D@C-LPs successfully bound to CLDN4 proteins that had become superficially exposed in pancreatic cancer owing to disruption of tight junctions, but showed reduced accumulation in the normal pancreas because access to CLDN4 in these tissues is hindered by intact tight junctions." (PMID 37237291, 2023). "This could be due to a more heterogeneous pattern of claudin-4 expression in the KPC pancreas compared to human pancreatic cancer xenografts as a result of the presence of different grade PDAC lesions within tissue, as suggested by our immunofluorescence results." (PMID 28842811, 2018). "Concomitant with downregulation of M markers, we noted augmented expression by IIT of Claudin-4 (CLDN4), an integral constituent of tight junctions and an inhibitor of invasion and metastasis in pancreatic cancer cells." (PMID 35565186, 2022). "c-CPE 194 also augmented the cytotoxicity of gemcitabine and S-1 (two anticancer drugs), reduced the expression of Claudin-4, and improved MAPK activity in a poorly differentiated pancreatic cancer cell line, PANC-1." (PMID 36077843, 2022). "AUC plots demonstrated that CLDN1 and CLDN18 represent potential predictors of thyroid cancer, and CLDN4 and CLDN18, predictors of pancreatic cancer." (PMID 29050243, 2017). "Very promising preclinical results are already reported for pancreatic cancer specific molecular targets like CEA, MMPs, claudin-4, RGD, and cholecystokinin-2 receptor." (PMID 25157372, 2014). "Claudin-4 expression is downregulated by TGF-β, whereas Ras signaling positively regulates claudin-4 expression in pancreatic cancer cells." (PMID 24009024, 2013). "Furthermore, five genes (KRT19, ALDOA, CLDN4, RAB27B, and GJB5) among the top 10 % coregulated genes were identified to have significantly elevated expression in pancreatic cancer compared to the normal pancreas." (PMID 40680814, 2025).
pancreatic cancer (continued). "Here, a CPE17-conjugated liposome (C-LP) that enables extensive accumulation in targeted pancreatic tumor tissues through the enhanced permeability and retention (EPR) effect and targeting of not hidden but exposed CLDN4 in pancreatic cancer was proposed." (PMID 37237291, 2023). "Unlike the E cell lines both QM lines were negative for Claudin-4 (CLDN4), a tight junctional protein and potent inhibitor of invasion and a metastatic phenotype of pancreatic cancer cells." (PMID 34572891, 2021). "No claudin-4 expression was detectable by Western blot in the human pancreatic carcinoma FAMPAC-1 cells or the human fibrosarcoma HT1080 cell line." (PMID 32414951, 2020). "For example, claudin-4 is highly expressed in poorly differentiated pancreatic cancer cells and is enriched at basolateral membranes rather than the apical junctional complex." (PMID 31783547, 2019). "Methylation of CLDN4 and CLDN5 has been reported in bladder and pancreatic cancer, respectively." (PMID 26198249, 2015). "Likewise, polysialic acid-based nanoparticles conjugated to cCpE then loaded with doxorubicin were shown to specifically target claudin-4-expressing pancreatic cancer and suppress tumor growth while exerting low toxicity to normal tissues." (PMID 35269525, 2022). "In well-differentiated HPAC (a pancreatic cancer cell line) duct epithelial cells, c-CPE 194 interrupted barrier functions without changing Claudin-4 expression while increasing MAPK phosphorylation." (PMID 36077843, 2022).
colorectal cancer (23 papers, 2005 to 2025). A primary or metastatic malignant neoplasm that affects the colon or rectum. "Also, the loss of Cldn4 expression in a colorectal cancer patient was associated with end stage disease." (PMID 35006480, 2021). "Furthermore, CLDN4 expression is associated with disease progression in, and thus has been suggested as a promising therapeutic target for ovarian, bladder, pancreatic, and colorectal cancer." (PMID 31040910, 2019). "A loss of claudin 4 expression at the invasive front in colorectal cancer correlates with cancer invasion and metastasis, and thus the finding in our study of a rather high level of CLDN4 in the NE tumour group, may reflect NETs in general lower malignant phenotype." (PMID 18827820, 2008). "In vivo experiments have confirmed that the CLDN4 exerts a carcinogenic effect in colorectal cancer through the activation of the PI3K/AKT/mTOR signaling pathway." (PMID 41461671, 2025). "Dysregulation of CLDN4 has been recognized as a common characteristic across different cancer types, like lung, gastric, breast, ovarian, and colorectal cancers." (PMID 40028163, 2025). "We additionally confirmed that TGFβ1 and CLDN4 engage in molecular structural interactions and that TGFβ1 inhibits CLDN4 transcription and protein expression in human colorectal cancer cell lines." (PMID 35281827, 2022). "In gastric, bladder, and colorectal cancers, hypermethylation of the CpG sequence in the CLDN4 gene promoter region leads to decreased CLDN4 expression." (PMID 35742959, 2022). "It was found that colorectal cancer in humans exhibited significantly elevated expression levels of claudin-4 compared with normal mucosa." (PMID 34638619, 2021). "We have reported that anti-claudin-4 (CLDN4) antibody enhances anti-tumoral effect of 5-FU by reducing barrier function of the tight junction in colorectal cancer." (PMID 31040910, 2019). "In this report, we aimed to determine the efficacy of targeting CLDN4 in colorectal cancer (CRC) using an anti-CLDN4 extracellular domain antibody, 4D3." (PMID 30647838, 2018). "HT29 colorectal cancer cells expressing the BRAF V600E mutation showed an increased activation of YAP and cytosolic CLDN4 whilst a decrease in membranous CLDN4, compared to HCT116 BRAF wild-type cells, which showed no YAP activation or changes in CLDN4 when treated with CPE for 24 h." (PMID 39340753, 2024). "Given the putative regulation of CLDN4 by AP-1 through AP-1-binding sites in its promoter, mRNA expressions of CLDN4 within molecular subsets of colorectal cancers were examined taking into consideration the presence of mutations in the upstream regulators KRAS and BRAF." (PMID 37998722, 2023). "Thus, CLDN4 overexpression appears to represent an early event in carcinogenesis in many cancers, and YAP activation by CLDN4 has been reported as a molecular biological background in precancerous lesions of colorectal cancer." (PMID 36982569, 2023). "Colorectal cancers have significant levels of CLDN4 expression." (PMID 35281827, 2022). "We have reported that TNFα decreases CLDN4 expression in colorectal cancer." (PMID 31040910, 2019). "Interestingly, human claudin-4 was overexpressed in colorectal cancer (CRC), suggesting that this barrier protein may be a potential marker of CRC." (PMID 38255781, 2024). "In colorectal cancer (CRC), CLDN1, CLDN2, CLDN4, and CLDN18 have been shown to either be upregulated or aberrantly expressed." (PMID 38540693, 2024). "Based on the currently available body of work on the protein expression of claudins in colorectal cancer, CLDN1, CLDN2, CLDN4, and CLDN18 have all been reported to be expressed in CRC." (PMID 38540693, 2024). "For example, HIF-1α is upregulated in colorectal cancer cell lines and contributes to angiogenesis by modulating the expression of EMT-related molecules claudin-4, E-cadherin and Vimentin." (PMID 34036383, 2021).
colorectal cancer (continued). "We found that NCOR1, NONO, and PPP1CC were more highly expressed in right-sided colorectal cancer, while CLDN4, EGR1, and ID2 were more highly expressed in left-sided colorectal cancer." (PMID 41174721, 2025). "The increase of claudin-4 in rat colon after chronic DMH exposure was consistent with the acute effect of DMH on IPEC-J2 cells, which may indicate an essential role of this protein in colorectal cancer development." (PMID 34638619, 2021). "The expression of claudin-4 is distinctly reduced in nonmelanoma skin cancer and colorectal cancer, while its expression is upregulated in several malignancies which might be used as diagnostic and therapeutic approach." (PMID 33282635, 2020).